CD4 (CD4 molecule)
Diseases named in the same sentence as CD4 in open-access papers (continued):
Sharing a sentence is not in itself a finding about the gene and the disease.
infection (continued). "CD4+ and CD8+ lymphocytes appeared in the blood of the vaccinated rats in significantly (p<0.05) higher numbers than in controls on day 35 after infection." (PMID 28333957, 2017). "During primary immune responses, both CD4+ and CD8+ T cell populations expanded by 14 days post-infection (dpi)." (PMID 28662714, 2017). "CD4+ and CD8+ cells specific for both H and N proteins were sources of IFN-γ throughout the course of infection." (PMID 28904342, 2017). "The numbers of total cells, lymphocytes, CD4+ cells, and CD8+ cells in all infected groups were increased at 3 days post-infection, and then decreased at 7 days post-infection." (PMID 28831046, 2017). "In comparison to untreated blood-derived CD4+ T-cells, the frequency of LAG-3 positive CD4 T-cells in LAG-3 silenced blood-derived T cells at times 72h and 96h post-infection, was essentially similar." (PMID 28880895, 2017). "However, the elicitation of higher magnitudes of CD4+ T cells by the DNA prime/MVA+gp120 protein boost vaccine could also be a concern for HIV vaccine development because responding CD4+ T cells have been hypothesized to enhance infections." (PMID 29021394, 2017). "Because the activation of CD4+ and CD8+ T cells against HSV involves DC migration from the infection site to draining LNs, we assessed the migration of DCs in vivo after inoculation with ΔgD-2 and WT virus." (PMID 29176979, 2017). "Differentiated THP-1 cells possess very low levels of CD4 at their surface, which necessitates pseudotyping incoming HIV-1 with other viral glycoproteins (such as VSV-G) to obtain efficient infection, though CD4-independent, viral entry." (PMID 29301198, 2017). "A significant negative correlation between pathology intensity and the percentage of CD4+ and CD8+ cells within SMLN lymphocyte pool at selected time points post-infection was recorded for both 1×104, and 1×106 IFU infected guinea pigs." (PMID 28678871, 2017). "In agreement with previous publications, neither Bcl6fl/flCD4-cre+/−, nor Sh2d1a−/− mouse strains showed alterations in the counts of CD4+ and CD8+ T cells, B cells and NK cells in the spleen prior to infection." (PMID 28888925, 2017). "In contrast, the number of CD4+ T-cells, CD8+ T-cells, and B-cells as well as their naïve and memory subsets significantly decreased as infection progressed." (PMID 29123522, 2017). "A significant reduction of CD4+ and CD8+ T lymphocytes in the MLN of S. mansoni-infected iCre-/+IL-4Rα-/lox Tam16 animals at week 18 post infection was observed." (PMID 28827803, 2017). "The development of CMV-specific T-cell responses in rhesus macaques is slightly different as both CD4+ and CD8+ CMV-specific T-cells appear at high frequency during primary infection and then persist indefinitely at high levels." (PMID 28428537, 2017). "To test the degree of CD4+ T cell proliferation due to low-dose LdWTLLO infection, we enumerated the LLO+ CD4+ T cells in the same groups of mice." (PMID 29312315, 2017). "Given the well-defined nature of CD8 CTL in comparison to CD4 CTL, comparisons of the cytolytic machinery of both T cell subsets can further our understanding of the relative impact of CD4 cytolytic activity in infection." (PMID 28167943, 2017). "Campbell and Spector identified that when resting CD4+ T cells were exposed to CCL2, upregulation of CXCR4 expression occurred, and the elevated CXCR4 expression increased infection by CXCR4-tropic HIV." (PMID 29085362, 2017). "Similar to infection with T. brucei rhodesiense, IFN-γ is produced predominantly by CD3+Thy1.2+TCRαβ+CD4+ T cells in BALB/c mice infected with T. congolense, as demonstrated by both immunohistochemistry and flow cytometry." (PMID 28936213, 2017). "We next assessed the functional status of LAG3 expressing-hepatic CD4 T cells and 2B4 expressing-hepatic CD8 T cells in late-stage infection." (PMID 28894272, 2017).
infection (continued). "Despite the relative abundance of total lymphocytes, the ratio of CD4+ to CD8+ cells between days 4 and 6 was significantly lower than for the controlled-infection status." (PMID 27799331, 2017). "The spleens of αβR−/− and αβR−/− λR−/− mice exhibited an increase in the levels of CCR7− CD62L− CD4+ and CD8+ T cells upon infection." (PMID 28811340, 2017). "Before HIV lowers CD4 cells, circulating CD8 cells will typically rise in response to the infection, resulting in a low CD4/CD8 ratio." (PMID 29095912, 2017). "All of these mice were protected against R. typhi-induced disease and survived the infection more than 150 days, demonstrating that CD8+ as well as CD4+ T cells are sufficient for protection." (PMID 27875529, 2016). "Microenvironmental factors in tissues enable resting CD4 T cells to be directly infected by HIV-1, and these cells are the dominant targets of early infection." (PMID 26728316, 2016). "TIM3, PD1, and LAG-3 were expressed on a substantial number of CD4+ and CD8+ T cells and their expression increased significantly late during infection (measured through week 44)." (PMID 26967901, 2016). "Considerable data exist from human and chimpanzee studies supporting the importance of HCV-specific CD4+ T helper and CD8+ cytotoxic T cells in clearance of primary infections and reinfections." (PMID 27362419, 2016). "Interestingly, the number of CD4 T cells, B cells, dendritic cells (DCs) and myeloid-derived suppressor cells (MDSc) were significantly lower in the neutrophil-depleted mice treated at week 4 post-infection and analyzed at 12 weeks post-infection compared to untreated or isotype-treated mice." (PMID 27690127, 2016). "IFN-γ produced early by NK cells is also important to orchestrate the ongoing adaptive immune response, contributing to differentiation of CD4+ Th1 and CD8+ T cells required for the control of the parasite multiplication occurring during the acute infection." (PMID 27891126, 2016). "Using the murine infection model for T. cruzi, splenic CD4+ and CD8+ T-cells were shown to express CD95 (Fas/Fas ligand apoptotic pathway) 2–3 weeks post infection." (PMID 27303406, 2016). "During infections with the apicomplexans Plasmodium or Toxoplasma, the emergence of IL-10+ IFN-γ+ CD4 T cells is required to limit excessive pathology." (PMID 26932389, 2016). "Antigen-specific CD4 T cells, instead, correlate with transient decline in HCV viremia and long-lasting control of the infection." (PMID 27186234, 2016). "Of note, within the CD4+ cell subset, IL17-producing cells were best represented in C3H/HeOuJ mice early after infection (day 2 and day 7)." (PMID 27848994, 2016). "We observed a statistically significant decline in the frequency of CD4+MHC class II− pDC at 1 and 2 days post-infection, then the levels recovered to baseline thereafter." (PMID 27008425, 2016). "Upon secondary infection, the increase and function of pathogen-specific CD8+ T cells, as well as pathogen control were significantly impaired in CD4-Cre A20fl/fl mice." (PMID 28004776, 2016). "Of note, HIV-specific CD4 and CD8 T cells arise with distinct kinetics during PHI, with specific CD4 T cells reaching their maximal frequency within few weeks post-infection, while CD8 T cells gradually increase for several months." (PMID 27746782, 2016). "This fits with a model in which CD4+ T cells are continuously activated during persistent HCV infection, especially when the infection aggravates.." (PMID 27034702, 2016). "Surprisingly, we detected CD4+ and CD8+ T cell responses to both SIVgag and SIVpol, indicating that, in the presence of an intact pentameric complex, UL36 is dispensable for infection of MCM by RhCMV." (PMID 27829026, 2016). "Twenty-four hours post-infection with M. bovis BCG, DCs were washed and co-cultured with autologous CD4+ T cells for 5 days to analyze the expansion of Treg population." (PMID 27080341, 2016).
infection (continued). "In contrast, CD4+YFP+GFP− T cell–derived cells expanded rapidly and upregulated IL-10 expression during secondary infection." (PMID 27630165, 2016). "CD4 and CCR5 are well-characterized receptors for HIV-1 entry and have been reported to function as interdependent accessory molecules for infection of target cells." (PMID 26667473, 2016). "The ability of effector CD4+ T cells to co-express IL-10 and IFN-μ is well established, and such cells have been described in several infection models." (PMID 26866695, 2016). "Both the alpha chain (IL-21R) and the common gamma chain (γc) of the IL-21 receptor were constitutively expressed by pulmonary CD4+ and CD8+ T cells, before and after infection." (PMID 27819295, 2016). "All together, these results confirmed the increase in the percentages of both CD4+ and CD8+ T CD62L−memory cells in the spleens from rexPy-immunized mice and after self-resolved infections." (PMID 27900319, 2016). "T cell activation in the CNS cannot readily be deduced by their phenotype as the majority of CD4+ and CD8+ T cells express a CD44+CD62LlowCD69+ effector phenotype throughout infection." (PMID 27708643, 2016). "MHC-II molecules continuously expressed in response to infection can load with antigenic peptides in the MHC compartment, and then export to the plasma membrane, where they prime CD4+ T cells." (PMID 27917375, 2016). "Thus, while T cells trafficking to the mucosa likely play a key role in the early response to invasion, CD4+ T-cell populations that persist in peripheral blood may help to prevent intravascular dissemination and persistence at secondary systemic sites of infection." (PMID 26810369, 2016). "Our data showed that after 16 dpi, infection led to the increase of relative proportions of CD4−CD8−, CD4+CD8−, and CD4−CD8+ populations." (PMID 27733201, 2016). "This is likely due to the marked depletion of CD4+ cells in the peripheral blood over the course of infection (cat 165 had 98 CD4 cells/μL) and the rarity of FIV-infected peripheral CD4+ cells (estimated to be 1 infected cell in 1000 CD4+ cells)." (PMID 29056720, 2016). "To test the effect of the PD-1/PD-L pathway blockade toward BCG replication in monocyte-derived macrophages (MDMs) controlled by T cells, we infected MDMs with BCG [multiplicity of infection (MOI) = 10] and co-cultured with CD4+ T cells (1:10)." (PMID 27924827, 2016). "We also posit that monocyte-macrophages could contribute to the development of long-lived sites of infection and can be used as a therapeutic target in eradicating virus either through cell based drug delivery or by their abilities to closely interact with other CD4+ target cells." (PMID 26996968, 2016). "Though we found the course of infection more protracted in mice treated with antibodies depleting CD4+ T cells or blocking IFN-γ signaling, the 1-time ivag challenge infection in treated mice was eventually controlled." (PMID 27606424, 2016). "It is known that, after infection by HIV-1, a significant fraction of CD4+ T cell subset expresses NKp44L, an activation ligand of the NKp44 receptor that is induced by a HIV gp41 peptide." (PMID 27382604, 2016). "Previous studies with human subjects have also shown that the increase in IFN-γ producing CD4+ and CD8+ T cells in response to Leishmania antigen was stimulated mainly in PBMCs of individuals cured of VL42, 48 and CL49 infection." (PMID 27624408, 2016). "Chitosan oral administration amplified the generation of CD11c+ DC, NK1.1+ NK cells, and DX5+ NK cells as well as CD4+ and CD8+ cells after infection by HSV-1." (PMID 28096567, 2016). "In both cell subsets, there was an overall decrease in Bcl2 expression at 7 days post infection compared to prior to infection, but to a greater extent for CD38+ CD4+ T cells." (PMID 27662621, 2016).
infection (continued). "Consistent with the similar numbers of LLO-specific memory CD4 T cells in WT and E-FABP-/- mice, LLO-specific memory CD4 T cells in WT and E-FABP-/- mice had similar frequencies of CD27+ cells throughout the infection." (PMID 27588422, 2016). "Here report that CD4+ RTE’s become partially activated and home to sites of infection in the liver, yet fail to acquire full effector function in the environment of the chronically infected host." (PMID 27658046, 2016). "Together, these results indicate a counter-balance between the effects of infection-induced NOTCH1 and SHH signaling cascades to regulate CD4+CD25+FoxP3+ Treg expansion." (PMID 27080341, 2016). "As expected, in the peripheral blood the number of HLA-DR positive CD4+ and CD8+ T-cells increased during late chronic stage of infection and were coincident with immune activation." (PMID 27484833, 2016). "IFNAR-/- B6 chimeric mice were depleted of CD4 and CD8 T cells via i.p. injection of monoclonal antibodies (clones YTS191 and YTS169 respectively) starting three days before infection with LASV." (PMID 27191716, 2016). "Regarding the influence of other parameters in the expression of these receptors, our analysis allowed us to establish any correlation between these and the CD4 T cell numbers, CD4/CD8 ratio, and days of infection." (PMID 27382604, 2016). "During a P. chabaudi infection CD4+ and CD8+ T cells were shown to produce IL-2231, whereas in a PbA infection γδ+ T cells beside others showed the highest ability to produce IL-22." (PMID 27311945, 2016). "In addition, infection with Pneumocystis significantly increases the levels of Pneumocystis-specific long-lived BMPCs, and numbers of BMPCs are not significantly affected by loss of CD4+ T-cells." (PMID 27242785, 2016). "Interleukin- (IL-) 4- and IL-10-producing CD4+and CD8+ T-cells were present in both La and Lb infection; however, interferon- (IFN-) γ-producing CD4+and CD8+ T-cells were detected only in Lb infection." (PMID 27073297, 2016). "Our data identify immunization regimens that induce antigen-specific memory T cell responses, involving both CD4 and CD8 T cells, that protect against infection with L. donovani." (PMID 27466350, 2016). "CD4+ T cells were isolated from the peripheral blood mononuclear cells (PBMCs) of healthy donors and then activated with anti-CD3 and anti-CD28 before infection." (PMID 27145859, 2016). "CAST/EiJ mice also had low numbers of T-helper (CD4+ cells) and cytotoxic cells (CD8+ cells) compared to C57BL/6 J and 129S1/SvImJ before and after infection." (PMID 26921172, 2016). "In lung homogenates harvested 14 days following infection, there was a significant expansion of IL-17+ cells; about 50% of these were CD3+, split equally between CD4+ Th17 cells and γδ T cells, while the CD3− IL-17+ cells were almost exclusively group 3 ILCs." (PMID 27698020, 2016). "HIV-1 drives DCIR expression on CD4+ T cells, and binding of HIV-1 to DCIR promotes infection of DCs and CD4+ T cells." (PMID 27584579, 2016). "Therefore, lower levels of integrated HIV-1 in purified resting CD4+ T cells isolated from HIV-1 patients treated with PI-based cART compared to HIV-1-infected patients treated with NNRTI-based cART could be critical to achieve control of infection." (PMID 27922055, 2016). "At day 1 post-infection, although an increase in CD3 levels was observed suggesting some migration of T cells towards the skin, CD4 transcription levels were drastically reduced." (PMID 26808410, 2016). "We demonstrate that IL-27 is critical for the induction of peripheral IL-10+CD4+ T cell responses and subsequent suppression of TH1 responses during the persistent phase of infection." (PMID 27926930, 2016). "The accumulation of CD3+CD4+and CD3+CD8α+ lymphocytes in the magnum was greater in the experimental than in the control group throughout the course of infection." (PMID 27846843, 2016).
infection (continued). "Neither did vaccine-induced CD8+ T cells contribute to blood-stage protection; rather, these cells contributed to pathogenesis, since all vaccinated mice depleted of both CD4+ and CD8+ T cells survived a challenge infection." (PMID 27245410, 2016). "Of note, a differential sensitivity of T cell subtypes to transformation has been observed in response to infection by HTLV-1, which predominantly transforms CD4+ T cells, while HTLV-2 mainly transforms CD8+ T cells." (PMID 27690235, 2016). "Importantly, the CD4 T cell response to pneumovirus is accelerated in mice with iBALT suggesting that the presence of iBALT in the lung leads to faster, more efficient pulmonary immune responses that promote rapid viral clearance and reduce morbidity after infection." (PMID 27446088, 2016). "CD4 CTL show perforin-dependent protection against lethal IAV infection in mouse models of infection, as well as in human studies of experimental infection or vaccination." (PMID 27014272, 2016). "Early after infection, many of the ESAT6-specific CD4+ T cells were polyfunctional based on their production of IL-2, IFNγ, and TNF." (PMID 26967901, 2016). "Moreover, studies performed on patients infected with HIV revealed that, during infection, PD-1 is up-regulated on monocytes and the interaction of PD-1 with PD-L1, expressed on other cell types, induced IL-10 production, which in turn led to CD4+ T cell dysfunction." (PMID 26700461, 2016). "Numerous studies have identified roles for both CD4+ and CD8+ T cells in clearance of acute lytic infection in the lungs." (PMID 27582728, 2016). "After primary infection, B cells are activated by antigens with the help of HCMV-specific CD4+ T cells, mainly Th2 cells, leading to the production of antibodies specific for a number of HCMV proteins." (PMID 28082969, 2016). "Of note, the number of IFN-γ-producing CD4+ and CD8+ T-cells was detected only in the Lb infection; however, on the evolution of the infection, the number of IFN-γ-producing CD4+ T-cells decreased, while the number of IFN-γ-producing CD8+ T-cells increased." (PMID 27073297, 2016). "We observed decreased numbers of total CD4+ and CD8+ T cells in the spleen and lung of Adamts5-/- mice at days 7 and 10 following infection." (PMID 27855162, 2016). "The increased ratio of IFN-γ: IL-10 producing CD4+ and CD8+ T cells in HVL after infection with LdCen1−/− and Ldp27−/− provide another correlate of protection." (PMID 27624408, 2016). "The level of PD-1-expressing cells followed similar trends and was reduced on CD4+ T cells in HIV-2 compared to both HIV-1 (P < 0.001) and HIV-D (P < 0.05) infections." (PMID 27525551, 2016). "The mRNAs specific for lymphocyte surface markers, including CD19, CD3, CD4, CD8, were up-regulated more significantly in response to the infection with HEP-Flury at 10 dpi." (PMID 27242764, 2016). "To probe this process in vivo, we isolated and sequenced CD3+/CD4+/CD62L- single cells from spleen and both mediastinal and mesenteric lymph nodes of Nippostrongylus brasiliensis (Nb)-infected mice 5 days post-infection." (PMID 27176874, 2016). "We found that naive CD4+ and CD8+ TREC contents decrease biphasically, with a rapid decline during the first year and a much slower decline during the chronic phase of infection." (PMID 27010200, 2016). "A statistically significant 2-fold increase in the proportion of CD4+MHC class II+ pDC observed at 2 days post-infection, the cell numbers rapidly declined at day 3 post-infection returning to pre-infection levels." (PMID 27008425, 2016). "Infection with EBOV/VP35m infection resulted in a significant increase, as compared to wt EBOV, in proliferating CD4+ cells secreting IFNγ, TNFα and IL-2." (PMID 27930745, 2016). "We found that α-IFNAR treatment significantly reduced CD25 expression on CD4 T cells responding to either Plasmodium or LCMV clone 13 infection." (PMID 27732671, 2016).